CX3CR1 (C-X3-C motif chemokine receptor 1)
Diseases named in the same sentence as CX3CR1 in open-access papers (continued):
Sharing a sentence is not in itself a finding about the gene and the disease.
infection (continued). "Using an intravascular labeling technique and a flow cytometry panel including CX3CR1 and Ly-6C antibodies, we ruled out CM and NCM blood contaminants and cells of DC origin and showed that the major Mtb-infected myeloid population in the lung interstitium several weeks after infection are MDMs." (PMID 40489538, 2025). "Although the correlation with Perf/GzmB expression may be prone to underestimation because of the prior release of cytotoxic molecules in vivo during ongoing infection, ∼5% of Perf/GzmB+ pMHCII tetramer+ CD4+ T cells lacked expression of Eomes, Hobit, and CX3CR1." (PMID 31308093, 2019). "However, neither CCR2-/- nor CX3CR1-/- mice demonstrated marked systemic spread of virus following dermal VACV infection, indicating that, unlike in the intranasal infection model, locally recruited macrophage populations are unlikely to play a role in restricting VACV to the skin." (PMID 28614386, 2017).
cancer (136 papers, 2009 to 2026). A tumor composed of atypical neoplastic, often pleomorphic cells that invade other tissues. "Our results suggest that surgery-related stress and cancer-associated inflammation in particular are mediated by CX3CR1+ PMN-MDSCs." (PMID 38433196, 2024). "Conversely, increased CX3CR1 expression was found to be associated to worse prognosis in a number of cancer types, reaching statistical significance for testis cancer." (PMID 39125578, 2024). "Analysis of the immune populations in human tumors using CIBERSORT showed that a higher M2 macrophage fraction was associated with higher CX3CR1 expression in multiple cancer types." (PMID 37771579, 2023). "Co-culturing irradiated LLC cells with CX3CR1-deficient monocytes, and macrophages resulted in reduced clonogenic survival and increased apoptosis of the cancer cells." (PMID 38001732, 2023). "Expression of CX3CR1 is heterogenous even between cancer subtypes is associated with histological grade and stage-dependent progression of various malignancies." (PMID 37770496, 2023). "CX3 chemokine receptor 1 (CX3CR1) is a protein encoded by the CX3CR1 gene and has been implicated in the dissemination of cancer cells and facilitation of cell survival and viability." (PMID 34066014, 2021). "Due to the high expression of CX3CL1 in bones, lungs and nervous tissues, circulating cancer cells with CX3CR1 expression cause metastasis in these organs and tissues." (PMID 32466280, 2020). "Accordingly, targeting TAMs via the CSF1/CSF1R or CX3CL1/CX3CR1 signaling pathway is an attractive therapy for cancers associated with increased numbers of TAMs (reviewed in refs.46,47)." (PMID 30237497, 2018). "Recently, fractalkine/CX3CR1 expression has been associated with many cancers, such as breast, colorectal, prostate, and gastric cancers." (PMID 28903329, 2017). "The polymorphic residues at positions 249 and 280 may be responsible for dysfunctional CX3CR1 variants, including variants identified in various cancers." (PMID 38731899, 2024). "CX3CR1 expression was associated with not only postoperative parameters but also preoperative parameters, which were speculated to relate with cancer-associated inflammation caused by latent presence of many immunosuppressive cells." (PMID 38433196, 2024). "DeAc-KLF5 upregulates CX3CR1 to enhance FGFR1 activation in PTEN-deficient cancer cells." (PMID 38781024, 2024). "In addition, the deficiency of CX3CR1 expression in macrophages altered the cytokine secretion with a decrease in interleukin 6, a crucial mediator of cancer cell survival and proliferation." (PMID 38001732, 2023). "Recently, numerous studies have implicated CX3CR1 in cancer progression." (PMID 36118530, 2022). "We reveal that inhibiting CX3CR1 results in sensitization to platinum drugs, displayed by replication fork stalling, impaired cell cycle progression, unresolved cisplatin-DNA adducts, and loss of cancer cell viability upon platinum treatment." (PMID 33810010, 2021). "It has been shown that sCX3CL1 also serves as a potent chemoattractant for these CX3CR1-expressing immune cells, enabling their chemotaxis towards the cancer niche and activation of their anti-cancer functions." (PMID 39011040, 2024). "Until now, only one high-affinity small-molecule inhibitor, AZD8797, and an anti-CX3CR1 nanobody are in phase 1 clinical trials to treat cancer pain and kidney disease, respectively." (PMID 38668112, 2024). "The NK1 cluster is characterized by high expression of CD16, CX3CR1, inhibitory KIRs and Tim-3 receptors, which take part in the recognition of ligands expressed by cancer cells that regulate cytotoxic reactions." (PMID 39457710, 2024). "The importance of the FKN/CX3CR1 signaling pathway in tumorigenesis and cancer metastasis results from its influence on cell adhesion, apoptosis, and cell migration." (PMID 38731899, 2024).
cancer (continued). "Natural variants of CX3CR1 may differ conformationally during activation, and conformational changes in CX3CR1 accompanying activation may be disrupted as a result of mutations and may be associated with various diseases, including changes in the risk of several cancers." (PMID 38731899, 2024). "Fractalkine/CX3C chemokine ligand 1 (CX3CL1) and its receptor CX3CR1 have been found to allow immature dendritic cells to migrate to cancer cells using the expression of their receptor CX3CL1." (PMID 38886862, 2024). "Extracting, organizing, and analyzing the TCGA database on the expression of CX3CL1 and its receptor CX3CR1 in cancer tissues and corresponding paracancerous normal tissues of OSCC patients by bioinformatics methods." (PMID 38915444, 2024). "As cited in Section 5.2.1 and Section 5.2.2, the results on the role of the FKN/CX3CR1 axis in common cancers remain clearly contradictory." (PMID 38731899, 2024). "CX3CR1 is expressed in various types of cancer cells, transmitting signals induced by CX3CL1 and participating in the proliferation and metastasis of malignant tumors." (PMID 38466034, 2024). "CX3CR1 activates pro-survival signaling pathways in normal and cancer cells thus promoting cell viability." (PMID 37770496, 2023). "Inhibition of CX3CR1 was reported to inhibit the cancer cell survival and increase sensitivity towards chemotherapy in NSCLC50." (PMID 37770496, 2023). "Studies also demonstrated that CX3CL1 and its unique chemokine receptor CX3CR1 played an essential role in cancer development." (PMID 37082943, 2023). "We next used an in-silico approach and grouped human cancers from TCGA based on their CX3CR1 expression into high CX3CR1 (top 50th percentile) and low (bottom 50th percentile) groups." (PMID 37771579, 2023). "At 7 days following cancer cell inoculation, microscopic foci were detected in the omentum of untreated groups of Cx3cr1+/GFP and Cx3cr1GFP/GFP mice." (PMID 37345662, 2023). "Saline-stimulated accumulation of CX3CR1+ SPM-like cells promotes implantation of cancer cells onto the omentum." (PMID 37345662, 2023). "CX3CR1 can be expressed in both cancer and immune-inhibitory myeloid cells to facilitate their migration." (PMID 37771579, 2023). "In summary, the CX3CR1 antibody can mitigate CX3CL1-CX3CR1 mediated pro-tumorigenic effects of aberrant myelopoiesis during cancer progression." (PMID 37771579, 2023). "To investigate the expression of the CX3CL1-CX3CR1 axis in human cancers, we used the TCGA and GTEx databases and examined the expression of CX3CR1 and CX3CL1 in human tumors versus their expression in normal tissue." (PMID 37771579, 2023). "Proverbially, the CX3CL1/CX3CR1 axis is significantly related to anti-inflammatory, anti-fibrosis, anti-rejection, and anti-cancer activities in the treatment of renal diseases." (PMID 36969169, 2023). "This indicated a clear role of miR-200-3p in increasing CX3CL1 and CX3CR1 expression in cancer cells." (PMID 37770496, 2023). "To date, only one high-affinity small-molecule inhibitor, AZD8797, and an anti-CX3CR1 nanobody are in phase 1 clinical trials to treat cancer pain and kidney disease, respectively." (PMID 35767622, 2022). "CX3CR1 is expressed at the surface of immune cells, such as T lymphocytes, NK, monocytes, granulocytes or DCs, but also on cancer cells." (PMID 36429101, 2022). "In consonance with this novel role of CX3CR1 in supporting FA DNA repair, we identified strong synergies between CX3CR1i and platinum in cell proliferation assays in a panel of cancer cell lines." (PMID 33810010, 2021). "The C-X3-C motif chemokine receptor 1 (CX3CR1) is an emerging anticancer target which expression correlates with worse overall survival in cancer patients undergoing DNA damaging treatments." (PMID 33810010, 2021). "Such functions of CX3CR1 have been observed not only in cancerous cells themselves but also in immune cells, such as macrophages that in turn synergize in cancer promotion." (PMID 34770776, 2021).
cancer (continued). "On the other hand, CX3CR1 appears to be involved in different functions, such as proliferation, cell adhesion, and migration, which contribute to tumorigenesis and cancer progression in gastric, pancreatic, or lung cancers." (PMID 34770776, 2021). "CCL2, CXCL10, and CX3CL1/CX3CR1 can serve as both favorable and unfavorable prognostic factors for cancers depending on cancer types." (PMID 31991604, 2020). "Blocking the CX3CR1 with a neutralizing antibody or transcriptional construct with CRISPi assistance results in reduced homing of cancer cells to bone and also of dendritic cells detected in bone." (PMID 32998351, 2020). "Recent reports describe also the role of CX3CR1 in the seeding of circulating cancer cells and suggest an essential impact of receptor antagonists in the treatment of metastatic cancer in clinical course." (PMID 32998351, 2020). "The EGFR family-dependent migration of cancer cells induced by CX3CR1 activation is probably a single signaling pathway, since the activation of STAT3 can take place via EGFR/ErbB1." (PMID 32466280, 2020). "One such chemokine that plays an important role in the cancer process is CX3C chemokine ligand 1 (CX3CL1) along with its receptor CX3C chemokine receptor 1 (CX3CR1)." (PMID 32466280, 2020). "The CX3CR1 gene promoter contains two Smad binding elements, thanks to which TGF-β increases the expression of CX3CR1 in microglia, although more detailed research on the regulation of CX3CR1 expression by TGF-β is required for different cancer cells." (PMID 32466280, 2020). "While CCL2, CXCL10, and CX3CL1/CX3CR1 can serve as favorable or unfavorable prognostic factors depending on the cancer types, CCL14 and XCL1 possess good prognostic value." (PMID 31991604, 2020). "Our previous study showed that the vertebral marrow sinusoids were full of CX3CL1, which plays an important role in the process of spine metastases derived from CX3CR1-expressing cancer cells." (PMID 32390803, 2020). "The expression levels of CX3CR1 mRNA among classical monocytes were significantly decreased in both groups of cancer patients at T0 when compared to the HG, with partial recovery at T1 in both groups of cancer patients." (PMID 32256215, 2020). "We observed miR-561-5p expression was higher in the metastatic lung niche than that in primary cancers, with fewer CX3CR1+NK cells detected in the metastatic lung niche." (PMID 31367257, 2019). "The mechanisms, by which the CX3CL1/CX3CR1 axis affects the pathogenesis and survival of cancer cells, are poorly explored." (PMID 29867042, 2018). "By analogy with its role in the leukocyte adhesion, CX3CL1 obviates the need for both the association with proteoglycans and other adhesion molecules to bind CX3CR1-expressing cancer cells rapidly and with high affinity." (PMID 28122354, 2017). "Because the cell characteristics are changed during EMT, it is possible that CX3CR1 is only expressed in mesenchymal cancer cells, which are prone to invasion and metastases." (PMID 28122354, 2017). "Our data show that CX3CR1 is expressed in the normal, cancer adjacent normal, inflammatory, and malignant fallopian epithelium." (PMID 26633537, 2015). "The CX3CL1/CX3CR1 axis plays an important function in the pathophysiology of several inflammatory, infectious, and neurological processes and in various forms of cancers." (PMID 24799766, 2014). "This review will summarize the multiple roles of the CX3CL1/CX3CR1 axis in the pathogenesis of inflammation and cancer." (PMID 24799766, 2014). "The expression of CX3CR1 in NK cells and some T cells subsets has provided the rationale to exploit the role of the chemokine/receptor in cancer immunotherapy setting the stage for potential therapeutic approaches." (PMID 24799766, 2014). "CX3CR1 was rarely detected in normal tissues, whereas CX3CR1 was observed in the inflammatory-like cells located in carcinoma tissue." (PMID 24245985, 2013).
cancer (continued). "Because of its unique structural and functional properties, FKN is an ideal candidate to mediate both adhesion and extravasation of CX3CR1-bearing circulating cancer cells." (PMID 21933397, 2011). "Androgens may promote the extravasation of CX3CR1-bearing cancer cells on an FKN concentration gradient, but their ability to adhere to the bone marrow endothelium is not altered." (PMID 38731899, 2024). "Considering these findings, CX3CL1 can increase the formation of lymphatic structures, change LV integrity, and simultaneously promote CX3CR1+ recruitment through LVs, thus resulting in increased metastasis of cancer cells to cervical LNs via the lymphatic pathway." (PMID 38775151, 2024). "To investigate whether CX3CL1 overexpression in cancer cells can attract the CX3CR1+ cells into the TME, we stained and counted the CX3CR1+ cells in the TME of MOC1 and MOC2 tumors." (PMID 38775151, 2024). "An increase in CX3CR1 expression increases sFKN-induced cancer cell migration." (PMID 38731899, 2024). "However, publications indicating the adverse effects of the FKN/CX3CR1 axis in promoting the growth and spread of various cancers are accompanied by an increasing number of contradictory reports." (PMID 38731899, 2024). "Multiple cancer types in TCGA shared common ISGS genes (CX3CR1, IL7, and HLA-B)." (PMID 39796714, 2024). "Since CX3CR1 is expressed on multiple cancer types, CX3CR1 antibody blockade could show therapeutic efficacy in multiple cancers." (PMID 37771579, 2023). "We next investigated survival in cancer patients based on CX3CR1 expression." (PMID 37771579, 2023). "Here we show that normal saline, when administered i.p. to mice, is prominently absorbed by the omentum, stimulates the expansion of milky spots and neoangiogenesis through the recruitment of CX3CR1+ monocyte/macrophages, and promotes implantation of cancer cells onto the omentum." (PMID 37345662, 2023). "Here we report a previously unknown role of CX3CR1 in FA-mediated DNA repair and evaluate for the first time the in vitro efficacy of targeting CX3CR1 with a small molecule inhibitor in the context of cancer." (PMID 33810010, 2021). "In cancer cells, CX3CR1 drives invasion, metastasis, proliferation, and survival." (PMID 33810010, 2021). "Hence, the interplay between CX3CR1 and FA repair provides novel potential therapeutic opportunities in cancers treated with DNA crosslinking agents." (PMID 33810010, 2021). "Notably, only ten percent of CX3CR1-expressing cells migrate to its soluble fractalkine ligand, suggesting that the mechanisms behind CX3CR1-driven cancer proliferation goes beyond ligand-mediated chemotaxis." (PMID 33810010, 2021). "A variety of genes were identified as being altered in LN tissue samples due to RRV infection, including cancer-associated genes activation-induced cytidine deaminase (AICDA), glypican-1 (GPC1), CX3C chemokine receptor 1 (CX3CR1), and Ras dexamethasone-induced 1 (RasD1)." (PMID 32017809, 2020). "As mCX3CL1 is an adhesion protein for cells with CX3CR1 expression, cancer with a simultaneous expression of both these proteins may aggregate, and thus, the migration of these cells is prevented." (PMID 32466280, 2020). "For this reason, an increase in CX3CR1 expression on cancer cells increases their migration." (PMID 32466280, 2020). "Therefore, some chemokines such as CCL2, CXCL10, and CX3CL1/CX3CR1 can be either favorable or unfavorable cancer prognostic factors depending on the cancer types." (PMID 31991604, 2020). "To further explore the clinical relevance of this axis, we performed in situ hybridization to determine miR-561-5p localization, in combination with immuno-staining of CX3CR1+NK cells, on serial sections of clinical samples from primary cancers and paired lung metastases." (PMID 31367257, 2019). "Thus, we suggest that cleavage of the ligands of the CXCR3 and CX3CR1 chemokine systems represents a potent immune escape mechanism in cancer." (PMID 31482487, 2019).